EDN1 (endothelin 1)
Diseases named in the same sentence as EDN1 in open-access papers (continued):
Sharing a sentence is not in itself a finding about the gene and the disease.
COVID-19 (31 papers, 2020 to 2025). A disease caused by infection with severe acute respiratory syndrome coronavirus 2. "This cluster also expresses EDN1 encoding for endothelin-1, a protein implicated in multiple lung diseases, and in endothelial and cardiovascular dysfunction in severe COVID-19." (PMID 40980495, 2025). "This study is aimed to investigate the association of endothelin-1 levels with the risk of 30-day and 12-month all-cause mortality in patients with prior COVID-19." (PMID 38003873, 2023). "High endothelin-1 during COVID-19 is associated with severe complications and increased mortality rates during hospitalization." (PMID 38003873, 2023). "Considering the published evidence on endothelin-1 in COVID-19, we cannot draw a definite conclusion with regard to the prognostic impact of this biomarker—further research is needed to answer this question." (PMID 35326373, 2022). "EDN1 mRNA levels were also similar in COVID-19 patients and control subjects when all patients were considered and, strikingly, were greater in mild patients as compared to controls or more severe patients (one-way ANOVA, post-hoc analysis)." (PMID 36009555, 2022). "The elevation of angiopoietin-2, thrombomodulin, endothelin-1, and vWF-A2 in fatal COVID-19 cases provides evidence for the involvement of endothelial injury in COVID-19." (PMID 33692097, 2021). "We assessed the prognostic implications of endothelial activation through measurement of endothelin-I precursor peptide (proET-1), the stable precursor protein of Endothelin-1, in a well-defined cohort of patients hospitalized with COVID-19." (PMID 33985491, 2021). "In addition, studies have shown that the patients with severe COVID-19 exhibit elevated levels of autoantibodies against the endothelin-1 type A receptor (ETAR), which mimic ET-1 and cause sustained vasoconstriction and inflammation." (PMID 40828447, 2025). "The proposed treatment does not significantly affect the concentration of endothelin-1, but a decrease in procalcitonin associated with additional antibacterial use was observed, especially in severe COVID-19." (PMID 40573382, 2025). "Additionally, EDN1 was found to be upregulated in the neurons of COVID-19 patients’ brains compared to the healthy control." (PMID 37239234, 2023). "Moreover, it is feasible that endothelin-1, one of the downstream mediators activated by angiotensin II is also increased in COVID-19 and it is known that endothelin-1 can induce HPSE expression as well." (PMID 33123154, 2020). "The proposed treatment does not significantly affect the concentration of endothelin-1, but a decrease in procalcitonin associated with additional antibacterial drugs was observed, especially in severe COVID-19, in addition to reduced D-dimers and procalcitonin values in all patients." (PMID 40573382, 2025). "We hypothesized that neutrophils expressing the pro-survival dual endothelin-1/VEGF-signal peptide receptor, DEspR, are apoptosis-resistant like DEspR+ cancer-cells, hence comprise a consequential pathogenic neutrophil-subset in ARDS and COVID-19-ARDS." (PMID 35379853, 2022).
migraine (31 papers, 2013 to 2025). "Histamine, leukotrienes, TNF-alpha, IL-6 and endothelin-1 released from MCs have been implicated in the pathophysiology of migraines." (PMID 33673856, 2021). "We also found associations between the expression of CALCA, EDN1, IL6, NOS3, VCAM1, and VEGF and measures of cerebrovascular function and migraine-related disability when menstrual phase (i.e., follicular, mid-cycle, or luteal) was accounted for." (PMID 38338971, 2024). "In terms of vascular pathophysiology, antiphospholipid antibodies (aPL) and β2GPI activate endothelial cells and subsequently regulate serotonin and endothelin-1, which is involved in vasoconstriction and leads to migraine aura." (PMID 39087012, 2024). "Related molecular markers such as endothelin-1 (ET-1) or nitric oxide (NO) have been determined in migraine." (PMID 32244987, 2020). "Other factors like endothelin-1 (ET-1), a potent vasodilator and mediator elevated in human plasma at the onset of migraine attacks, sensitizes nociceptors to mechanical-stimuli via endothelial cell-mediated release of adenosine triphosphate leading to hyperalgesia." (PMID 35110596, 2022). "Studies propose that EDN1, a vasoconstricting peptide primarily produced in vascular endothelium, could regulate vascular tone and take part in vascular homeostasis and migraine pathophysiology." (PMID 32185192, 2020). "This hypothesis is augmented by abnormal levels in nitric oxide and endothelin-1 and higher prevalence of migraine in CSX patients." (PMID 27708590, 2016). "Thus, Interictal plasma endothelin-1 level is an unlikely marker for migraine." (PMID 37277733, 2023). "However, it is crucial to realise that rapid progress can also be made in migraine specifically by targeted follow-ups (such as for the rs9349379/EDN1/ET-1 study), given that we now have a set of well-characterised loci waiting for such detailed characterisation." (PMID 30634909, 2019). "Finally, increased plasma concentrations of endothelin-1 had been described in both migraine and renal disease patients; this might be the reason for their co-morbid association." (PMID 24392299, 2013).
liver fibrosis (29 papers, 2006 to 2025). "Liver sinusoidal and epithelial cells also have a focal role in liver fibrosis after liver injury, as these cells release endothelin-1 (ET-1) and nitric oxide (NO)." (PMID 40786064, 2025). "In light of the pro-fibrogenic role of Endothelin-1, VECadCre+Cc1fl/fl mice developed hepatic fibrosis with bridging chicken-wire deposition of collagen fibers in their liver parenchyma at 8 months of age even when fed a regular chow diet." (PMID 39640841, 2024). "Consistently, plasma Endothelin-1 levels were elevated in AlbCre+Cc1fl/fl mice starting at 6 months of age preceding hepatic fibrosis." (PMID 39640841, 2024). "Endothelin-1 (ET-1), another angiogenic factor, has also been reported to be involved in liver fibrosis." (PMID 33557759, 2021). "Most of the pro-fibrotic genes were associated with the “Hepatic fibrosis/hepatic stellate cell activation” pathway, with the exception of COL12A1 and EDN-1, the latter being among the top upregulated genes." (PMID 31969876, 2019). "Moreover, endothelial CEACAM1 expression gradually declined with the advanced hepatic fibrosis stage and in parallel to the progressive increase in plasma Endothelin-1 levels of patients with MASH." (PMID 39640841, 2024). "In addition, ANP prevents dimethylnitrosamine (DMN)-induced hepatic fibrosis in rats and antagonizes endothelin-1 (ET-1)-induced calcium increase and cell contraction in cultured human hepatic stellate cells (HSCs)." (PMID 33777158, 2021). "Among the other factors affecting liver fibrosis is endothelin 1 (ET-1), a peptide widely distributed in the liver, which induces HSC proliferation and the decrease of insulin-like growth factor (IGF), involved in the differentiation, proliferation, and apoptosis of hepatocytes." (PMID 31671675, 2019). "The profibrogenic role of endothelin-1 (ET-1) in liver fibrosis remains disputed." (PMID 17062135, 2006). "Upregulation of endothelin-1 (ET-1), vascular endothelial growth factor (VEGF), laminin (LN), and type IV collagen by LSECs during liver fibrosis has been reported." (PMID 28770223, 2017). "Other key proliferative, fibrogenic and contractile stimuli in hepatic fibrosis are PDGF-C, TGF-β and EDN1, respectively." (PMID 21949825, 2011).
renal fibrosis (29 papers, 2006 to 2026). A final common manifestation of a wide variety of chronic kidney diseases characterized by glomerulosclerosis and tubulointerstitial fibrosis. "Evidence from experimental models of ADPKD suggests that elevated endothelin-1 (ET-1) drives cyst growth, renal fibrosis and loss of renal function, but whether ET-1 is elevated in humans with ADPKD is uncertain." (PMID 26923419, 2016). "Renal tubular cells with IS-related injury release transforming growth factor-β or other chemokines such as intercellular adhesion molecule-1, monocyte chemoattractant protein-1, osteopontin, and endothelin-1, which promote renal fibrosis." (PMID 39759603, 2024). "In this study, we confirmed that treatment with R-715 up-regulated endothelin-1, accompanied by increased renal fibrosis." (PMID 34669782, 2021). "ETA receptor activation is primarily responsible for vasoconstriction, cell proliferation, proteinuria and the induction of renal fibrosis induced by endothelin-1." (PMID 29267497, 2017). "By detecting the levels of the fibrosis-related proteins SMA, ECA, TGF-β, and VIMENTIN, as well as the renal tubular injury–related factors AKLOTHO and EDN1, our results reveal that the extent of renal fibrosis and tubular injury in the WTDI/R mice was more severe than in the KODI/R mice." (PMID 39656542, 2024). "Interestingly, in this model, TIF was also prevented by bosentan, a mixed ETA-ETB endothelin receptor antagonist, but worsened by BMS-182874, a selective ETA receptor antagonist, suggesting a key role of endothelin-1 (ET-1) acting via the ETB receptor subtype in triggering renal fibrosis." (PMID 31330886, 2019). "In the feline renal fibrosis process, several major pro-fibrotic mediators are involved, including TGF-β, transglutaminase 2 (TG2), endothelin 1 (ET1), and the renin-angiotensin-aldosterone system (RAAS)." (PMID 39858257, 2025).
glomerulosclerosis (27 papers, 2011 to 2025). A hardening of the kidney glomerulus caused by scarring of the blood vessels. "In addition, endothelin-1 (ET-1) has been associated with vasoconstriction, kidney injury, mesangial hyperplasia, glomerulosclerosis, fibrosis, and inflammation, and thus endothelin receptor antagonists have been proposed as potential treatments for DKD." (PMID 34769288, 2021). "The crosstalk signaling between podocyte dysfunction and depletion in glomerulosclerosis is mediated by Endothelin-1 (EDN1)/Endothelin Receptor Type A (EDNRA)-dependent mitochondrial dysfunction." (PMID 34576149, 2021). "In support of this observation, mitochondrial-targeted ROS scavengers and endothelin antagonists inhibit the release of EDN1, thus reducing mitochondrial oxidative stress and endothelial cell dysfunction, thereby preventing glomerulosclerosis." (PMID 32733268, 2020). "Blocking aldosterone with spironolactone significantly reduced proteinuria, glomerulosclerosis, tubulointerstitial injury and endothelin-1 expression, and significantly increased Dot1a and Af9 expression." (PMID 23077601, 2012). "ET-1 actions may result in glomerulosclerosis (discussed in Endothelin-1 promotes the development of glomerulosclerosis, TIF, and renal inflammation)." (PMID 27009050, 2016). "Endothelin-1 promotes the development of glomerulosclerosis, TIF, and renal inflammation." (PMID 27009050, 2016).
colorectal cancer (25 papers, 2001 to 2025). A primary or metastatic malignant neoplasm that affects the colon or rectum. "Public genomic datasets were analyzed to confirm EDN1 upregulation in colorectal cancer (CRC) and its association with poor prognosis." (PMID 41425720, 2025). "In contrast, endothelin-1 has been implicated in HO-1-induced enhancements in stemness in colorectal cancer; however, in our study, the expression of endothelin-converting enzyme associated with ALA did not change." (PMID 37047157, 2023). "It is shown that IL-6 produced by MSCs increases endothelin 1 (ET-1) expression in colorectal cancer (CRC) cells, resulting in the activation of AKT1 and ERK in endothelial cells which lead to tumor neo-angiogenesis enhancement." (PMID 39981232, 2025). "Inhibiting YAP signaling restores sensitivity to oxaliplatin, suppresses proliferation, and enhances apoptosis, underscoring the therapeutic potential of targeting the EDN1-YAP axis to overcome chemoresistance in colorectal cancer." (PMID 41425720, 2025). "Collectively, these results demonstrate that EDN1 upregulation promotes oxaliplatin resistance in colorectal cancer via YAP pathway activation." (PMID 41425720, 2025). "The secretion of interleukin-6 (IL-6) from MSCs increases the secretion of endothelin-1 (ET-1) in colorectal cancer cells, which activates Akt and ERK in endothelial cells, thus enhancing their capacities for vessel formation." (PMID 36824409, 2023). "An interesting paracrine angiogenic interaction between BM-MSC-secreted IL-6, colorectal cancer-secreted endothelin-1 (ET-1), and endothelial cells has been reported." (PMID 35741711, 2022). "Our initial approach for mimicking the situation in CC531 colorectal cancer liver metastasis was to induce transient Edn1 knockdown by siRNA." (PMID 32194414, 2020). "When added to the culture medium, melatonin inhibited edn-1 mRNA expression (which is the initial step in ET-1 synthesis) and the release of ET-1 from the colorectal cancer cells." (PMID 28420185, 2017). "MLT inhibits edn-1 mRNA expression (the first step in ET-1 synthesis), ECE-1 protein expression and the release of ET-1 from colorectal cancer cells in vitro." (PMID 26225957, 2015). "Endothelin-1 (ET-1) is a vasoconstrictor peptide which stimulates proliferation in vitro in different cell types, including colorectal cancer cells." (PMID 11742499, 2001). "Collectively, our in vivo findings provide strong evidence that pharmacological blockade of EDN1 using bosentan enhances the anti-tumor efficacy of oxaliplatin and may represent a promising strategy to overcome oxaliplatin resistance in colorectal cancer." (PMID 41425720, 2025). "Indeed, EDN1 is a growth factor playing a critical role in tumorigenesis; it is frequently secreted in several tumors, such as liver, breast and colorectal cancers, in which enhances tumor growth by promoting angiogenesis." (PMID 35878242, 2022). "Furthermore, MSCs secrete cytokines like angiopoietin-1 (Ang-1) and IL-6 in colorectal carcinoma, in turn stimulating cancer cells to secrete endothelin-1 (ET-1), which in turn activates ERK and AKT paths in tumor endothelial cells, resulting in tumor vessel formation and mobilization." (PMID 33472580, 2021). "To evaluate the therapeutic potential of EDN1 inhibition in vivo, we performed xenograft assays using HT29 colorectal cancer cells." (PMID 41425720, 2025). "Following treatment with OXP (10 μM, 24 h), a generalized elevation of EDN1 mRNA expression levels was observed in colorectal cancer (CRC) tumor cells, with OXP-sensitive cell lines (e.g., HCT8) exhibiting a more pronounced upregulation of EDN1 expression." (PMID 41425720, 2025). "Collectively, these findings demonstrate that oxaliplatin-induced overexpression of EDN1 promotes the nuclear translocation of β-arr1, thereby facilitating the activation of YAP signaling and contributing to chemoresistance in colorectal cancer." (PMID 41425720, 2025).
colorectal cancer (continued). "For example, primary colorectal cancer derived SW480 cells, which were exposed to DAC, exhibited an almost 100fold increase in mRNA expression of EDN1, whereas the increased EDN1 expression in metastatic SW620 cells was 50 fold lower than that in SW480 cells, although it was still significant." (PMID 32194414, 2020).
systemic sclerosis (25 papers, 2008 to 2025). A chronic disorder, possibly autoimmune, marked by excessive production of collagen which results in hardening and thickening of body tissues. "HLA-B*35 is associated with a high risk of developing PAH in systemic sclerosis by influencing the production of endothelin-1 (ET-1) and decreasing endothelial nitric oxide synthase (eNOS)." (PMID 26106387, 2015). "Several studies have evaluated the efficacy of targeting the vasoconstrictor endothelin-1 for the treatment of systemic sclerosis-associated vascular disease." (PMID 22121371, 2011). "Endothelin-1 (ET-1) is a vasoactive and profibrotic peptide that plays a pivotal role in diseases such as systemic sclerosis (SSc) and pulmonary arterial hypertension (PAH), by inducing fibrosis and vascular remodeling." (PMID 36359285, 2022). "It has been known for many years that systemic sclerosis is characterized by increased levels of plasma endothelin 1 (ET-1); hence, further research on medications affecting endothelin levels is reasonable." (PMID 35268401, 2022). "The aim of this study was to investigate the serum concentration of metabolic adipose tissue factors: adiponectin, resistin, leptin and endothelial proteins: endothelin-1, fractalkine and galectin-3 in patients with systemic sclerosis." (PMID 31667578, 2020). "In conclusion, an increased serum level of resistin associated with increased endothelin-1 and fractalkine level and decreased adiponectin level may indicate a significant role of the adipose tissue in the development and progression of vascular abnormalities in patients with systemic sclerosis." (PMID 31667578, 2020). "Endothelin-1 (ET-1) plays a pivotal role in vasoconstriction, fibrosis, and inflammation, the key features of systemic sclerosis (SSc)." (PMID 26090478, 2015). "Systemic sclerosis (SSc) has higher circulating levels of endothelin 1 and is characterized by a first inflammatory stage followed by a chronic fibrotic stage notably in the lung." (PMID 24286074, 2013). "In addition, endothelin-1 plays a very important functional role in progression of systemic sclerosis." (PMID 29928282, 2018). "Endothelin-1 (ET-1) is important in the pathogenesis of systemic sclerosis (SSc)." (PMID 27209208, 2016). "We compared year-long changes in endothelin-1 (ET-1), galectin-3 (Gal-3), renal indices (eGFR, ACR), and quantitative CT densitometry in COPD and systemic sclerosis-associated ILD (SSc-ILD)." (PMID 41010963, 2025). "Endothelin-1 (ET-1) serves as a key mediator of vascular hypertrophy, cellular proliferation, inflammation, and fibrosis, and is overexpressed in the plasma of patients with systemic sclerosis, particularly those with DUs and/or pulmonary arterial hypertension (PAH)." (PMID 41226942, 2025). "Therefore, it could be possible that IRE1α-mediated endothelin-1 expression has a role in systemic sclerosis pathogenesis." (PMID 29928282, 2018). "In the early phase of Ssc, the vascular dysfunction is presented by the aberrant cell–cell interaction by increased expression of adhesion molecules, such as VCAM-1, ICAM, E-selectin, and the growth factors as TGFβ, endothelin-1 (ET-1), and PDGF." (PMID 39210206, 2024).